OAS1 (2'-5'-oligoadenylate synthetase 1)
Diseases named in the same sentence as OAS1 in open-access papers (continued):
Sharing a sentence is not in itself a finding about the gene and the disease.
infection (continued). "Both, OAS1 and IFTIM3 have been shown to interfere with RSV replication and limit productive infection." (PMID 33133080, 2020). "The results showed that the expression of antiviral genes (e.g., PKR, OAS1, and Mx2) and inflammatory cytokines (e.g., IFN-α and TNF-α) were significantly reduced within 0–4 h post-infection (P < 0.05)." (PMID 32133381, 2020). "We noted a minor increase in OAS1 and MxA levels in MCF7/pS cells indicating that OAdmCherry infection induces a type I IFN antiviral response." (PMID 31100952, 2019). "The up-regulated TF ZFHX3 targets seven genes in module AD_M25, where two genes OAS1 and RSAD2 are detected in infection pathways, and the other five genes FAM122B, SAMD9, TRIM21, USP18 and IFIT3 are also known to be related to infectious disease." (PMID 30598117, 2018). "The genes OAS1 and RSAD2 play important roles in infection pathway, imposing an activation effect on several infectious disease response pathways detected in AD compared to normal samples." (PMID 30598117, 2018). "Real-time qRT-PCR results showed that the presence of 200 U/mL IFN-β dramatically increased the mRNA levels of ISG15, OAS1, and MX1 in LC, macrophages, and SC at 8 h post-infection." (PMID 28239382, 2017). "We observed approximately 0.5 to 1-log fold greater expression of ISG15, EIF2AK2, OAS1, IFNA4, and IFNB1 in the lungs of rWSN-GH-NS1-Y84F infected mice on days 1 and 3 post-infection compared with the lungs of rWSN-GH-NS1-wt infected mice." (PMID 28498306, 2017). "All three types of sensors, MDA5, OAS1-3, and PKR, are known to recognize dsRNA, suggesting that the PAMP(s) relevant for their activation during infection is/are of viral origin." (PMID 28158275, 2017). "For OAS1, the highest mRNA level was observed in cells treated with IFN-λ1/DENV-2 at 18 h post-infection." (PMID 26411318, 2015). "Up-regulation of ISGs such as OAS1, MX1, and the transcriptional regulator ISGF3γ were observed within 24 h of infection in iHLCs." (PMID 25826356, 2015). "In the present study, the IFN-stimulated genes (IFIT1, IFIT3, MX1, ISG15, OAS1, and IFI6) were dramatically increased at 16 h and 24 h post infection, which should trigger powerful antiviral functions." (PMID 23527143, 2013). "Within metabolic inflammation, convergent evidence also implicates the IFN-OAS axis in T2DM: in human skin and skeletal muscle transcriptomes, OAS1/OAS2/OAS3 are significantly upregulated and enriched for infection-related pathways, indicating tissue-level activation of interferon responses in T2DM." (PMID 41569989, 2026). "The results showed that SVA infection could significantly downregulate the expression of IFNB, IFIT2, IFIT1 and OAS1 induced by poly (I:C), but this inhibitory effect was weakened in VP2 knockdown cells." (PMID 41319264, 2026). "In the brain, infection with Bov342 induced the expression of type-I (Ifna5, Ifnb), -II (Ifng), and -III (Ifnl2) interferons (IFN), interferon stimulated genes (ISGs) (Isg15, Ifit1, Mx1, Oas1), and pro-inflammatory cytokines (Il1b, Il6, and Tnfa) at endpoint." (PMID 40410375, 2025). "Proteomic data from PBMCs collected at 0, 3, and 6 dpi confirmed that both strains induced activation of intracellular sensors (RIG-I, OAS1, and TRIM25) and transcriptional factors such as EIF2AK2, although activation was consistently stronger during MA08 infection." (PMID 39992151, 2025). "At 24 h post-infection, HMPV boosted ISG15, OAS1, MX1, and IRF7 by multiples of ten magnitudes." (PMID 40732740, 2025). "LTR16B2:ERVL and MER74A:ERVL were significantly upregulated under infection, and showed positive correlation with the expression of OAS1, whereas CapAeg_1.233:ERVK was specifically upregulated in embryos and also showed positive correlation with OAS1." (PMID 40176799, 2025). "Several ISGs, including MX1, MX2, and OAS1, were upregulated in 170-infected animals at many different time points but were generally only significantly upregulated in CL8 animals at weeks 1 and 2 post-infection." (PMID 38317183, 2024).
infection (continued). "Furthermore, only infection with Omicron resulted in a significant induction of Ifna5 and Ifnb, ISG-driven antiviral effectors Mx1, Oas1, and Viperin, and pro-inflammatory mediators Cxcl10 and Il6." (PMID 38742107, 2024). "Furthermore, the levels of OAS1, MX1, and ZAP expression in the prestimulated and post stimulated IPEC-J2 cells were found to be significantly different following L. mucosae G01 infection (p < 0.05)." (PMID 39171258, 2024). "Our data suggest that human OAS1, OAS2, and RNase L are each essential for the correct regulation of immunity to SARS-CoV-2 but are otherwise largely redundant in natural conditions of infection." (PMID 36538032, 2023). "Here again, stimulation with IFN-α2 served as positive control to demonstrate the intrinsic capacity of hiPSC-macrophages to mount an antiviral response, as shown by significant upregulation of OAS1 mRNA following IFN-α2 treatment, even under the condition of CF VZV-eGFP/ORF23 infection." (PMID 37287975, 2023). "OAS1 and IFI6 were overexpressed in individuals with a high viral load of infection." (PMID 37389217, 2023). "Results showed that MX1, MX2 and OAS1 were over-expressed in SARS-CoV-2-infected A549 cells (p < 0.01 for MX1, ISG15, and OAS1; and p < 0.05 for MX2), and Calu-3 cells (p < 0.05 for MX1, ISG15, and OAS1; and p < 0.01 for MX2) compared with mock infection." (PMID 36298734, 2022). "Decreases in CNS antiviral genes could certainly result in the development of a more robust infection in this compartment, and a recent study noted an inverse correlation in expression of MX1, OAS1, and MX2 expression with SIV RNA levels in the CNS." (PMID 35494221, 2022). "Notably, multiple antiviral proteins were also dramatically decreased in PAMs during the PRRSV-ADE infection, including ISG15, ISG20, IFIT1 (ISG56), IFIT2 (ISG54), IFIT3 (ISG60), IFIT5 (ISG58), OAS1, Mx1, RSAD2, TRIM22, TRIM25 and TRIM34, except for TRIM52." (PMID 36680075, 2022). "While we did not observe differences in IFNAR1, IRF3, STAT1, nor ISG15 expression induced by the two strains, IFNβ, LPG2, RIG1, and OAS1 were significantly induced after infection with Mb3601, but not H37Rv." (PMID 34307535, 2021). "As expected, infection with the LAI virus, which was prepared using method A and induced high levels of IFN-I in the supernatant, upregulated the expression of many ISGs, such as IFIT1 and OAS1." (PMID 34844429, 2021). "Viral RNA analysis revealed neither OAS1 isoform impacted IAV RNA levels significantly at 24 hr post-infection." (PMID 34342578, 2021). "Furthermore, a dampened induction of several downstream ISGs, including MX1, OAS1, ISG-15, and viperin was observed on day 4 post-infection." (PMID 33653328, 2021). "Sindbis virus (SINV) or vaccinia virus (VACVΔE3L) infection of wild-type (WT) or OAS1-KO (knockout), OAS2-KO, or MAVS-KO RoNi/7 cells, but not RNase L-KO or OAS3-KO cells, induces robust RNase L activation." (PMID 31719180, 2019). "In contrast, neither M. leprae infection not TLR2/1 activation of IL-15 MΦ induced upregulation OAS1 as a result of infection or following TLR2/1 stimulation." (PMID 30300363, 2018). "However, gene expression levels of IF1H1, OAS1, IFN-β, CXCL10 and CCL5 were increased in islets following infection with E16 and E30 compared to the mock-infected control." (PMID 28146100, 2017). "to 48 h.p.i., albeit at much higher levels for the qRT-PCR data, OAS1 and MYD88 exhibited highly similar upward trend of upregulated expression levels for both data sets across all infection time-points, although at much enhanced levels for the qRT-PCR data (respectively)." (PMID 26892458, 2016). "Therefore, qRT-PCR analysis of IFNβ, OAS1, MxA, TNFα, IL-6 and viral RNA (vRNA) expression was performed in the context of WNVNY99 and WNVNSW2011 infections." (PMID 25884341, 2015). "In cells pre-treated with IFN-λ1 and then infected, MX1 mRNA increased between 18 and 48 h post-infection, although not as much as OAS1." (PMID 26411318, 2015).
infection (continued). "Interestingly, at the early phase of infection (24 hpi), MoDCs infected with WNVNY99 had reduced levels of vRNA (p < 0.05), IFNβ mRNA,OAS1 mRNA and MxA mRNA compared to MoDCs infected with WNVNSW2011." (PMID 25884341, 2015). "We therefore examined gene expression for several important interferon-related genes (IFNα2, IFNα4, IFNβ, IFNαβR, IFNγ, IFNγR, Irf3, Irf7, Mx1, Oas1, IFITM1, IFITM2), along with inflammasome-related genes IL-1β and NLRP3, and chemokines CCL5, CCL7, and CCL12 at d1 post-infection." (PMID 26110868, 2015). "Since OAS1 is an IFN-stimulated gene, we also measured IFNβ1 in these samples and observed a significant increase above control at day 6 (p = 0.002) and day 12 (p = 0.007) post infection." (PMID 19247438, 2009). "OAS1 mRNA was detected in uninfected tissue from all 12 donors (data not shown), and expression of total OAS1 mRNA was induced ∼2 fold by WNV compared with donor-matched uninfected control tissue at day 3 post-infection (p = 0.01)." (PMID 19247438, 2009). "In addition to the OAS1 region, CapAeg_1.233:ERVK:LTR (chr1:141284178-141285910) proximal to another important immune gene, TMPRSS2, was altered during endometrium development and under infection." (PMID 40176799, 2025). "Because of the incomplete of the annotation of goat genome, we cannot rule out whether there are an unknown infection-inducible OAS1 isoform or ERV-derived lncRNA." (PMID 40176799, 2025). "Whether infection may induce the expression of MER74A and LTR16B2, independent of infection-induced OAS1, remain to be determined." (PMID 40176799, 2025). "SARS-CoV-2-Δ8 infection showed a trend of increasing IFN signaling (IFNλ3, interferon-stimulated gene [ISG15], and MX1, P values 0.4337, 0.1126, and 0.2285, respectively) as compared to WT at 3 dpi, while reducing IFN-stimulated gene levels (IFNλ3, ISG15, IFIT1, OAS1, and XAF1) at 6 dpi." (PMID 37623322, 2023). "tularensis LVS-infection; a significant upregulation of genes involved in RAS pathway including Ccl2, Nfkb, p38 Mapk, Ras, Stat1, Stat3 and Tnf-α; and an upregulated expression of IFN-γ pathway genes such as Bak, Bax, Ifit, Ifn-γ, Irf, Isg, Oas1, Psmb8, Ptpn2, Stat and Tap1." (PMID 37266014, 2023). "Likewise, 231/pS cells exhibited an increase in MxA expression in response to OAdmCherry infection, whereas OAS1 was not detectable in these cells, even after OAdmCherry infection." (PMID 31100952, 2019). "Additionally, we observed increases in the expression of EIF2AK2 (24-fold), OAS1 (10-fold), IFNA4 (10-fold) and IFNB1 (10-fold) in the lungs of rWSN-GH-NS1-Y84F infected mice treated with IFN-β on day 1 post-infection compared with the lungs of infected, but untreated mice." (PMID 28498306, 2017). "Further, the comparative potency of nc886 may reflect a role in OAS1/RNase L-mediated cell death in situations when infection has passed the ‘point of no return’." (PMID 25477390, 2015). "Together these data suggest that OAS1 activity may influence the probability of initial infection, but not the severity or symptomatic quality of infection, after WNV exposure in man." (PMID 19247438, 2009). "The study of the expression of IFNs, antiviral factors, cytokines and chemokines after 6 and 24 h pots-infection with PRRSV showed significant increases in IFN-β, IFN-γ, Mx1, and OAS1 only at h 24 after the viral challenge, compared to non-infected pAMs." (PMID 41155369, 2025). "The infection increased IFN-β, IFN-λ1, Mx1, OAS1, PKR, and RIG-I but it did not alter IFN-α and IFN-λ3 expressions." (PMID 40565228, 2025). "Specifically, suppression of IFI6 and OAS1 was impaired by HAdV-B7 when RuvBL2 was knocked down, but not of IFIT1 nor IFIT2, while only OAS1 expression in HAdV-B14 infection was affected by RuvBL2 knockdown." (PMID 38940561, 2024). "For example, CD4+ T cells, but not monocytes, upregulated OAS1, OAS2, and DDX58 upon infection in all animals." (PMID 38317183, 2024).
infection (continued). "Quantification of OAS1 isoforms relative to PDIA3 revealed a significant increase in the correlation of p46, but not p42, to PDIA3-positive membranes during infection, suggesting that p46 is recruited to sites of WNV replication." (PMID 34342578, 2021). "Thus, activation of RNase L during VACVΔE3L infection of bat RoNi/7 cells was dependent on RNase L and OAS3 but not OAS1, OAS2, or MAVS, similar to our findings with SINV." (PMID 31719180, 2019). "Interestingly, we found that ISGs such as OAS1 and ISG15 were markedly increased in vaginal tissue of Oasl1−/− mice even in the absence of infection." (PMID 26750802, 2016). "However, the majority of antiviral ISGs, including OAS1, MX2, IFI6, IFITM1, IFI27, and IFTM2, were downregulated in cells transduced with MyD88 (in the presence or absence of infection) and were also downregulated in cells infected with UL88-deficient HCMV vs wild-type HCMV." (PMID 40638072, 2025). "Interestingly, whereas TLR4 inhibition (TAK-242, 10 μM) did not alter enhanced OAS1 and IRF7 expression in response to hypoxic priming and SARS-CoV-2 infection, it completely abolished the expression of chemokine ISGs CCL2 and CXCL10, despite the fact that the infection rate was not affected." (PMID 37377965, 2023).
tumor (51 papers, 2009 to 2025). "We aim to systematically investigate the expression pattern and biological functions of OAS1, assess its association with patient prognosis, and elucidate its relationship with the tumor immune microenvironment and potential response to immunotherapy." (PMID 41584451, 2025). "We examined the relationship between OAS1 expression and Tumor Mutational Burden and Microsatellite Instability, both of which have been linked to the formation of tumor neoantigens and the effectiveness of immune checkpoint blockade therapy." (PMID 37928544, 2023). "OAS1 was positively associated with the expression of numerous immune checkpoint genes and tumor mutational burden (TMB)." (PMID 37746262, 2023). "To evaluate OAS1 genetic alteration in cancers, we conducted a comprehensive analysis of the OAS1 gene mutation status in various tumor types." (PMID 37928544, 2023). "Additionally, we evaluated the correlation between OAS1 expression and tumor pathological stage and found significant associations in BLCA, PAAD, LUAD, and SKCM." (PMID 37928544, 2023). "Forest plot revealed that OAS1 expression was associated with the prognosis of several tumor types." (PMID 37928544, 2023). "The level of OAS1 gene expression is closely linked to tumor onset and progression." (PMID 38103068, 2023). "Our cellular experiments also implicated that OAS1 plays a supportive role in tumor progression." (PMID 37746262, 2023). "Furthermore, in our study, OAS1 was found to be associated with the expression of a variety of tumor-infiltrating immune cells, which is consistent with a recent study." (PMID 35898870, 2022). "Furthermore, we analyzed the impact of OAS1 promoter methylation on prognosis and found that higher levels of OAS1 promoter methylation were associated with better prognosis in tumor types such as BCRA (p = 0.016), LGG (p < 0.001), LIHC (p = 0.017), and LUSC (p = 0.097)." (PMID 37928544, 2023). "This study aims to identify key epithelial cell-derived signature genes driving tumour progression, construct a reliable prognostic model, and further explore the biological functions of a pivotal gene, OAS1, in BLCA." (PMID 41584451, 2025). "The expression level of OAS1 varies across different tumor types and plays distinct roles in different cancers." (PMID 41584451, 2025). "For instance, IFIT1, IFIT3, IFI-16, ISG15, MX1, and OAS1 have been shown to have tumor-suppressive function." (PMID 40563638, 2025). "STAT1 is a TF overexpressed in OC and can act as oncogene or tumor suppressor depending on the disease stage and tissue heterogeneity, whereas OAS1 was shown to be upregulated in several cancers to promote tumor anti-viral responses." (PMID 39634630, 2024). "Together with the increased expression of nc886 in cancer, these data suggest another tumor surveillance model in which the increased nc886 during tumorigenesis activates OAS1 and induces apoptosis to eliminate pre-cancerous cells." (PMID 39409154, 2024). "For more comprehensive insight into the influence of OAS1 within the tumor immune microenvironment, we further analyzed the OAS1 expression and specific immune cell types." (PMID 37928544, 2023). "In order to investigate the role of OAS1 in tumor immune response, we also analyzed the relationship between OAS1 and immune checkpoint gene expression in pan-cancer." (PMID 37746262, 2023). "Our findings revealed a positive correlation between OAS1 expression and M2 macrophage infiltration in several tumor types using both algorithms." (PMID 37928544, 2023). "We also examined the relationship between OAS1 expression and tumor pathological stage using the GEPIA tool." (PMID 37746262, 2023). "High OAS1 expression was correlated with poor prognosis in 6 tumor types, while high OAS1 expression was correlated with good prognosis in 2 tumor types." (PMID 37746262, 2023). "According to the expression level of OAS1, tumor patients were divided into high and low OAS1 expression groups." (PMID 37746262, 2023).